LCN2 (lipocalin 2)
Diseases named in the same sentence as LCN2 in open-access papers (continued):
Sharing a sentence is not in itself a finding about the gene and the disease.
endometrial cancer (27 papers, 2012 to 2025). Primary or metastatic malignant neoplasm involving the endometrium (mucous membrane that lines the endometrial cavity). "Others found that increased LCN2 tissue expression is associated with aggressive characteristics and a poor prognosis in women with endometrial cancer." (PMID 38645429, 2024). "Increased LCN2 expression is associated with aggressive features and poor prognosis in endometrial cancer." (PMID 22559235, 2012). "Taken together, our data support associations between LCN2 expression and aggressive tumor features, distant metastatic spread and reduced survival in endometrial cancer." (PMID 22559235, 2012). "Recent studies of endometrial cancer have implicated LCN2 in tumor progression." (PMID 22559235, 2012). "LCN2 serum levels play an important role in the diagnosis of endometrial cancer, and upregulation of LCN2 expression promotes drug resistance in endometrial cancer cells and inhibits the ferroptosis process." (PMID 39931061, 2025). "A study with 85 high-grade endometrial cancer tissue samples showed strong LCN2 expression using immunohistochemical detection." (PMID 38645429, 2024). "In line, immunohistochemical localization of LCN2 (as well as its receptor SLC22A17) was indicated LCN2 to be a prognostic factor in endometrial cancer." (PMID 38645429, 2024). "Consistent with this, LCN2 was found to be a component of the key signature in the onset of endometrial cancer in the glandular uterine epithelium, as its expression increased in precancerous atypical endometrial hyperplasia." (PMID 38645429, 2024). "In endometrial cancer, there is not only a strong expression of LCN2 in the tissue, but also in the serum of the patients." (PMID 38645429, 2024). "Their results showed that LCN2 promotes the survival of endometrial cancer cell lines via the PI3K pathway in a stressful environment and in an iron-dependent manner." (PMID 38645429, 2024). "They evaluated the pattern of LCN2 expression in patients with endometrial cancer and found higher serum LCN2 concentrations in patients with endometrial cancer compared to patients with normal endometrium." (PMID 38541074, 2024). "A study by Miyamoto and co-workers provided information on signaling pathways of LCN2 in endometrial cancer." (PMID 38645429, 2024). "In a study that included 123 women, out of whom 52 had endometrial cancer, significantly lower median serum levels of LCN2 were found in a group of patients with normal endometrium compared to the endometrial cancer group." (PMID 38645429, 2024). "In vitro experiments confirmed the role of LCN2 in enhancing endometrial carcinoma cell survival and migration by mediating cytokine production." (PMID 38645429, 2024). "Although it is known from endometrial cancer that LCN2 can mediate the expression of cytokines, there are hardly any studies regarding PCa." (PMID 35053376, 2022). "Microarray analysis showed that LCN2 was the most highly upregulated protein in neoplastic endometrial epithelia, correlating with increased proliferation and invasiveness of endometrial carcinoma cells." (PMID 34062746, 2021). "An LCM-microarray study showed that the LCN2 expression was upregulated during the malignant process of endometrial carcinoma, and the forced expression of LCN2 promoted cell growth and increased the invasive potential of endometrial carcinoma cells." (PMID 34062746, 2021). "Multiple LCN2-immunopositive proteins have also been found in conditioned media from human endometrial cancer cell lines and in plasma samples from patients with chronic myelogenous leukemia." (PMID 26949374, 2016). "In order to clarify the function of LCN2 in endometrial carcinoma cells, we herein focused on the effects of LCN2 on cell migration and cell survival under various stresses such as cisplatin and ultraviolet irradiation, which are typical DNA-damaging factors." (PMID 27168162, 2016).
endometrial cancer (continued). "We previously identified LCN2 as an up-regulated gene in endometrial carcinoma, and found that the overexpression of LCN2 and its receptor, SLC22A17, was associated with a poor prognosis." (PMID 27168162, 2016). "We found that cell migration and resistance to serum starvation, cisplatin, and ultraviolet irradiation were enhanced by LCN2, suggesting that it confers malignant potential to endometrial carcinoma cells." (PMID 27168162, 2016). "The present study also indicated that LCN2 increased the resistance of endometrial carcinoma cells, HHUA, RL95-2 and HEC1B, to CDDP." (PMID 27168162, 2016). "Further studies are needed to clarify the relationship between the expression of LCN2 and stemness of endometrial carcinoma cells." (PMID 27168162, 2016). "Immunohistochemical staining was performed using a human LCN2 antibody on a population-based series of endometrial cancer patients collected in Hordaland County (Norway) during 1981-1990 (n = 256)." (PMID 22559235, 2012). "High expression of LCN2 protein together with its receptor SLC22A17 has been related to poorer prognosis among endometrial cancer patients." (PMID 22559235, 2012). "The aim of the present study was to investigate LCN2 in endometrial cancer in relation to clinico-pathologic phenotype, angiogenesis, markers of epithelial-mesenchymal transition (EMT), and patient survival." (PMID 22559235, 2012). "In total, 125 (49%) of the endometrial cancers were positive for LCN2 cytoplasmic protein expression, while 131 (51%) of the cases were negative (median SI value was 0)." (PMID 22559235, 2012). "In endometrial cancer cell lines, LCN2 seems to trigger cytokine production, IL8 being the highest, and this response has been suggested to improve cell survival functions by preventing apoptosis and increase cell migration." (PMID 22559235, 2012). "Furthermore, others found that stimulation with LCN2 protein purified from mouse uterine fluid induced apoptosis in the RL95-2 endometrial cancer cell line." (PMID 38645429, 2024). "Furthermore, forced expression of LCN2 led to increased proliferation and invasion in the human endometrial cancer cell lines Ishikawa and HEC1B." (PMID 38645429, 2024). "LCN2 mRNA and protein expression were strong in human patients with endometrial hyperplasia and, suggesting that it is involved in the tumorigenic process leading to endometrial carcinoma." (PMID 38645429, 2024). "Furthermore, high expression of LCN2 or the LCN2-MMP-9 heterodimer is associated with worse outcomes in patients with gastric, breast, and high-grade endometrial cancers." (PMID 32575507, 2020). "According to numerous studies in which LCN2 was quantitated by immunological methods such as immunohistochemistry, ELISA, gel zymography, and Western blots in urine, LCN2 has been proposed as an early marker of bladder, brain and endometrial cancer." (PMID 27729871, 2016). "These LCN2 functions conferred malignant potential to endometrial carcinoma cells." (PMID 27168162, 2016). "However, the functions of LCN2 in endometrial carcinoma cells, as well as the intracellular mechanisms involved remain undetermined." (PMID 27168162, 2016). "Furthermore, the forced expression of LCN2 enhanced the proliferation and invasion of endometrial carcinoma HEC1B and Ishikawa cells." (PMID 27168162, 2016). "Eight endometrial cancers (3%) had a very strong cytoplasmic expression of LCN2 (SI = 9)." (PMID 22559235, 2012). "In this study, we demonstrate that LCN2 expression is associated poor outcome in endometrial carcinoma and with aggressive features, including the non-endometrioid histologic type, high grade and solid tumor growth." (PMID 22559235, 2012). "LCN2 expression is speculated to be involved in balance between cell death and proliferation in uterine tissue remodeling and is important in the progression of endometrial cancer." (PMID 38645429, 2024).
endometrial cancer (continued). "In addition, Lin and colleagues used the human endometrial carcinoma cell line RL95-2 to gain new insights into the LCN2 signaling mechanism and found that it is induced in a time-dependent manner by glucocorticoid stimulation (dexamethasone) and under starvation conditions." (PMID 38645429, 2024). "These functions of LCN2 may increase the malignant potential of endometrial carcinoma cells." (PMID 27168162, 2016). "Here, we found an association between LCN2 expression and ER-PR negative endometrial cancers." (PMID 22559235, 2012). "To further confirm the correlation between LCN2 and SAA1/2 expression and endometrium cancer, we analyzed The Cancer Genome Atlas (TCGA) cohorts and observed significantly upregulated LCN2 and SAA1/2 expression in EEC cases compared with normal samples." (PMID 36273006, 2022). "Therefore, LCN2 may be a potential molecular target for the treatment of endometrial carcinoma." (PMID 27168162, 2016). "The expression of LCN2 mRNA was the highest in HHUA and RL95-2 cells and lower in HEC1B cells among the endometrial carcinoma cell lines tested." (PMID 27168162, 2016). "Serum LCN2 and MMP9 levels may be good clinical tools for the auxiliary diagnosis of early-stage endometrial cancer." (PMID 39973816, 2024).
liver disease (27 papers, 2012 to 2025). "Using ethanol-fed and CCl4-induced liver fibrosis in Lcn2-deficient mice, we demonstrate that LCN2 plays a key role in liver fibrogenesis and portal hypertension." (PMID 32968110, 2020). "Here, we describe the association of LCN2 hepatic and circulatory levels with liver fibrosis, portal hypertension and disease severity in patients with AH." (PMID 32968110, 2020). "Thus, fecal lipocalin-2 levels may emerge as a marker of microbiome dissimilarities, which are associated with neurological, tumor and liver diseases." (PMID 37189804, 2023). "So, we highlight that LCN2 can emerge as a potential biomarker for differentiating stages of liver disease." (PMID 39832399, 2025). "It has been known that LCN2 has demonstrated the ability to distinguish between various stages of liver disease." (PMID 39832399, 2025). "Most interestingly, urinary lipocalin-2 levels were low in pre-renal acute kidney injuries, higher in hepatorenal syndrome and highest in acute tubular necrosis, which are the main causes of acute liver injury in liver cirrhosis." (PMID 37189804, 2023). "In agreement with many previous studies, the authors found that LCN2 serum levels and gene expression correlated well with disease severity, liver fibrosis, and portal hypertension." (PMID 37638032, 2023). "Their study showed, in alcoholic hepatitis patients, a correlation between the disease severity and portal hypertension with increased hepatic Lcn2 expression and Lcn2 serum levels." (PMID 34327512, 2021). "We found hepatic LCN2 expression and serum LCN2 level markedly increased and correlated with disease severity and portal hypertension in patients with AH." (PMID 32968110, 2020). "We explored the role of intrahepatic LCN2 in human alcoholic hepatitis (AH) with advanced fibrosis and portal hypertension and in experimental mouse fibrosis." (PMID 32968110, 2020). "We provide evidence that LCN2 is massively overexpressed in the liver from patients with AH and its expression correlates with the degree of fibrosis and portal hypertension." (PMID 32968110, 2020). "Because HSCs are liver-specific pericytes that play a key role linking fibrosis and portal hypertension, we demonstrated that LCN2 promotes EDN1 synthesis in HSCs during liver fibrogenesis." (PMID 32968110, 2020). "In this review, we will summarize some of the major findings of LCN2 in the pathogenesis of organ disease with a special emphasis on inflammatory liver diseases." (PMID 27729871, 2016). "Most popular for quantification are diverse ELISA tests that have been proved to be the most sensitive and quick method to detect LCN2 elevation in early stages and conditions of experimental and clinical liver disease including FLD, NASH, and HCC." (PMID 27729871, 2016). "In this review, we summarize experimental and clinical findings linking LCN2 to the pathogenesis of liver disease." (PMID 27729871, 2016). "In this review, we have summarized experimental and clinical findings linking LCN2 to liver disorders." (PMID 27729871, 2016). "Here we will first focus on some of the most recent reports on LCN2 expression and organ disorders to understand the possible major functions of LCN2 and subsequently highlight the importance of LCN2 in the pathogenesis of hepatic disease." (PMID 27729871, 2016). "Consequently, elevated concentrations of LCN2 occurring during fatty liver disease induced by elevated energy intake should limit progression of hepatic disease itself through MC4R-dependent suppression of appetite." (PMID 37638032, 2023). "These two cytokines, MPO and MMP-9, may act in concert with the LCN2 protein and are involved in liver diseases, such as NAFLD/NASH." (PMID 36012166, 2022). "LCN2 contributes to liver fibrosis and portal hypertension in AH and could represent a new therapeutic target." (PMID 32968110, 2020). "We partially uncovered the mechanisms of LCN2-induced fibrosis and portal hypertension in AH." (PMID 32968110, 2020).
liver disease (continued). "In summary, our results suggest that LCN2 massive hepatic expression in patients with AH could favor fibrosis and portal hypertension, two of the main predictors of patients’ morbidity and mortality." (PMID 32968110, 2020). "Importantly, hepatic LCN2 mRNA expression in patients with AH closely correlated with the degree of portal hypertension (r = 0.47, p = 0.0005), a major pathophysiological event." (PMID 32968110, 2020). "Moreover, we demonstrated that LCN2 has a hepatoprotective effect during liver injury, implying that LCN2 acts to suppress the development and aggravation of liver disease." (PMID 29234288, 2017). "The relevance of LCN2 in liver fibrogenesis and portal hypertension is unknown." (PMID 32968110, 2020). "A subpopulation of LCN2-expressing CD24+ LPCs was activated and expanded in ductular reaction foci with liver disease progressed." (PMID 37784089, 2023). "First, there is a lack of specificity: LCN2 is involved in various pathological conditions beyond liver diseases, including renal damage, brain injury, and cancer." (PMID 39832399, 2025). "The upregulation of LCN2 expression in damaged hepatocytes and infiltrating immune cells has been observed in various liver diseases, including hepatitis, alcoholic liver disease, and non-alcoholic steatohepatitis." (PMID 37784089, 2023). "The findings that hepatic LCN2 expression closely correlated with disease severity (i.e. ABIC and MELD scores), the degree of portal hypertension (i.e. levels of HVPG) and the expression of key fibrogenic genes (i.e. COL1A1, TIMP1) highly suggest a pathogenic role for LCN2 in AH." (PMID 32968110, 2020). "A combination model composed of CCL20 and LCN2 may serve as a more efficient tool for distinguishing HCC from nonmalignant liver diseases." (PMID 35308139, 2022).
lupus nephritis (27 papers, 2013 to 2025). Glomerulonephritis in the context of systemic lupus erythematosus. "Along these lines, a recent meta-analysis found urinary lipocalin-2 levels suitable for the detection of lupus nephritis." (PMID 37189804, 2023). "Possibly, determination of urinary lipocalin-2 can be helpful in the evaluation of lupus nephritis in general." (PMID 24171081, 2013). "Previous studies showed that up-regulation of lipocalin-2 in SLE can promote the in vivo and in vitro differentiation of Th1 cells via the IL-12/STAT4 signalling pathway, thereby causing an immune imbalance and leading to lupus nephritis (LN)." (PMID 36249802, 2022). "In conclusion, in the current study we found that urinary lipocalin-2 may act as a useful marker of lupus nephritis and provide additional clinically relevant information about disease activity to that given by the established marker." (PMID 24171081, 2013). "Notably, serum lipocalin-2 levels appeared not suitable as a diagnostic biomarker for lupus nephritis." (PMID 37189804, 2023). "An important clinical conclusion is that adding measurement of urinary lipocalin-2 to the routine follow-up of LN patients, particularly those with biopsy-proven disease, may result in earlier diagnosis of lupus nephritis, and therefore less delay in institution of appropriate treatment." (PMID 24171081, 2013). "Studies have shown that certain inflammatory factors and chemokines, such as TWEAK, MCP-1, NGAL, OPG, Lipocalin-2, IP-10, and CXCL-16, are involved in the pathogenesis of lupus nephritis." (PMID 39958362, 2025). "Studies have shown that LCN2 promotes Th1 cell differentiation in an autocrine or paracrine manner through the IL-12/STAT4 pathway, leading to lupus nephritis (LN) deterioration." (PMID 37488573, 2023). "SLE patients with lupus nephritis presented increased urinary LCN2 concentrations compared to those without nephritis." (PMID 39403549, 2024). "In the present study, we found that urinary lipocalin-2/creatinine level was higher in patients with lupus nephritis compared to those without nephritis and significantly correlated with proteinuria." (PMID 24171081, 2013). "Indeed, SLE patients with lupus nephritis had higher urinary lipocalin-2 levels compared to those SLE patients without kidney disease." (PMID 37189804, 2023). "Second, the study is cross sectional and was not designed to determine whether serial urinary lipocalin-2/creatinine measurements can predict the onset and progression of SLE nephritis." (PMID 24171081, 2013). "Interestingly, SLE patients with lupus nephritis presented increased urinary LCN2 concentrations compared to those without nephritis, suggesting that this adipokine may be a potential marker of the severity of renal involvement in patients with SLE." (PMID 39403549, 2024). "Exposure of kidney mesangial cells to these pathogenic autoantibodies strongly upregulated lipocalin-2 expression, which raised the possibility that urinary lipocalin-2 levels could serve as a biomarker to discriminate between SLE patients with or without lupus nephritis." (PMID 37189804, 2023).